CLDN3 (claudin 3)
Diseases named in the same sentence as CLDN3 in open-access papers (continued):
Sharing a sentence is not in itself a finding about the gene and the disease.
prostate carcinoma (continued). "Western blots show that Cldn3 and Cldn4 levels are higher in metastatic prostate cancer cells (PC3, LNCaP, and DU145) compared to normal prostate cells (RWPE-1)." (PMID 35006480, 2021). "Claudin-3 and claudin-4 are the most frequently deregulated in cancers and are found highly expressed in ovarian, breast, and prostate cancers." (PMID 32197343, 2020). "Plasma derived exosomal survivin and claudin 3 was also found to be high in prostate cancer patients, suggestive of its role in prostate cancer diagnosis." (PMID 31013716, 2019). "Further, CLDN-3 and -4 expressing cells from a human prostate carcinoma bone marrow metastase were killed in vitro by adding the CPE to the culture medium." (PMID 27690019, 2016). "Interestingly, plasma levels of PTEN and claudin-3 were inversely correlated in the plasma from patients with prostate cancer." (PMID 40723233, 2025). "Similarly, elevated levels of claudin-3 have been reported in prostatic cancer patients compared to controls." (PMID 38188015, 2023). "In conclusion, our findings strongly indicate that epigenetic silencing of CLDN3 is a common event in CRPC that could be useful as a molecular marker for the prognosis of prostate cancer patients and to discriminate aggressive from indolent prostate tumors." (PMID 36614243, 2023). "We hypothesize that Cldn3 or Cldn4 may be potential therapeutic targets for the management of prostate cancer." (PMID 35006480, 2021). "The similar expression patterns of Cldn3 and Cldn4 in prostate cancers may suggest a coordinated regulation and raises the possibility for an effective targeted treatment strategy." (PMID 35006480, 2021). "In addition, Cldn4 is overexpressed in primary and metastatic prostate cancer, and Cldn3 is strongly expressed in the majority of prostate cancers." (PMID 35006480, 2021). "Knocking down Cldn3/Cldn4 affects prostate cancer cell growth and survival and may have therapeutic implications." (PMID 35006480, 2021). "In addition, we treated LNCaP prostate cancer cells with siCldn3 and noted a 70% knockdown of Cldn3 expression after 2 weeks." (PMID 35006480, 2021). "Moreover, claudin-3 and claudin-4 have become promising candidates in the new treatment strategy against prostate cancer." (PMID 32197343, 2020). "For example, claudin-3 and claudin-4 were expressed at high levels in endometrioid adenocarcinoma and prostate cancer; claudin-10 expression was up-regulated in hepatocellular carcinoma and thyroid papilloma; claudin-2 has been reported to be up-regulated in thyroid cancer and endometrial cancer." (PMID 24245968, 2013). "We observed that CLDN3 was silenced in the cell line recapitulating a more aggressive and therapy-resistant stage of prostate tumors (abl), but it was expressed in androgen sensitive prostate cancer cells (LNCaP), representing initial stages of prostate cancer development." (PMID 36614243, 2023). "In this line, our data show that the loss of CLDN3 expression could be preventing cell–cell interactions favoring cell invasion, thus suggesting that the more aggressive phenotype of androgen-independent prostate cancer cells could be explained, at least in part, by CLDN3 epigenetic silencing." (PMID 36614243, 2023). "Therefore, it seems that claudin-3 might act as a biomarker of prostate cancer to be possibly used in the early detection of neoplasm." (PMID 32197343, 2020). "In both types of tissue, increased expression of claudin-3 was seen in the majority of cases examined, and was seen more frequently than in non-neoplastic tissue, indicating that it may serve as an important biomarker for prostate cancer." (PMID 21255442, 2011). "For high-grade prostate cancer (HG-PCa), the smMIP-method identified 8 markers, and the microarray identified 17 markers, with FOLH1, FAP and CLDN3 being common across both platforms." (PMID 39595976, 2024).
prostate carcinoma (continued). "Based on the knockdown of Cldn3 and Cldn4 using PC3 and LNCaP prostate cancer cells, siCldn3_4 and siCldn4_1 were selected for all subsequent functional studies." (PMID 35006480, 2021). "In examining the protein levels of Cldn3 and Cldn4 after 72 h, we generated a knocked down of greater than or equal to 70% for both PC3 and LNCaP human prostate cancer cells when treated with siCldn3s and siCldn4s." (PMID 35006480, 2021). "Human prostate cancer PC3 and LNCaP cells were transfected with Cldn3 or -4 small interfering RNAs (siRNAs)." (PMID 35006480, 2021). "The most interesting ones appeared to be claudin 3 (CLDN3) and alpha-methysacyl-CoA racemase highly expressed in prostate cancer and filamin C (FLNC) and keratin 5 with highest expression in normal prostate tissue." (PMID 24477410, 2014). "Furthermore, decreasing the level of CLDN3 and CLDN4 proteins through knockdown of CLDN3 and CLDN4 in prostate cancer resulted in a 30–40% decrease in prostate cancer cell growth, a 60–65% reduction in cell viability, and cell migration." (PMID 38731853, 2024). "The result of targeting Cldn3 and Cldn4 expression on the growth and viability of prostate cancer cells has not been elucidated." (PMID 35006480, 2021). "Furthermore, exposing Clostridium perfringens enterotoxin (CPE), a potent cytolytic toxin, to its natural receptors Cldn3 and Cldn4 has been shown to induce CPE-mediated cytotoxicity in prostate cancer cells and ovarian tumors." (PMID 35006480, 2021). "Consistent with our finding, CLDN3 was previously reported to express at a reduced level in EBVaGC, while DPP4 is an androgen receptor-induced tumor suppressor gene that was downregulated in some cases of prostate cancer." (PMID 32841292, 2020). "Specifically, we generated a Cldn3 knockdown of 85% and 97% for PC3 and LNCaP human prostate cancer cells, respectively, when treated with siCldn3_4 and a Cldn4 knockdown of > 99% and 98% for PC3 and LNCaP human prostate cancer cells, respectively, when treated with siCldn4_1." (PMID 35006480, 2021). "Human prostate carcinoma metastases derived cell lines PC3 and LNCaP lack CLDN-3 and -4 expressions, whereas human non-neoplastic prostate epithelium expresses the CLDNs-3 and -4." (PMID 27690019, 2016).
gastric cancer (19 papers, 2005 to 2025). A primary or metastatic malignant neoplasm involving the stomach. "The downregulation of claudin-3 is associated with proliferative potential in early gastric cancer." (PMID 36010553, 2022). "In relation to gastric cancer, the hypermethylation of the Claudin-11 promoter has been associated with increased invasive potential, and the hypermethylation of the Claudin-3 promoter is considered a predictor of poor prognosis in advanced gastric adenocarcinoma." (PMID 39296813, 2021). "However, apart from E-cadherin, only few studies investigated the correlation of TJ proteins with gastric cancer prognosis: reduced expression of claudin 3 has been associated with a poorer prognosis in intestinal-type tumours, yet failing to gain statistical significance in multivariate analysis." (PMID 19142187, 2009). "It is of particular interest that elevated expression levels of CLDN3 in gastric cancer influence tumor cell permeability, facilitating their traversal across the basement membrane and extracellular matrix, thus potentially contributing to oncogenesis." (PMID 39336798, 2024). "On the other hand, claudin-3 and -4 expressions in high-grade gastric dysplasia–early gastric carcinoma predicted higher incidence rates of synchronous or metachronous gastric carcinomas." (PMID 37627123, 2023). "Claudin-3 and claudin-7 were expressed in 25.4% and 29.9% of the gastric cancer tissues, respectively." (PMID 31861759, 2019). "For instance, the transcription factor Cdx2 can enhance the expression of claudin-3 and -4 in gastric cancer cells, and the transcription factor RUNX3 can enhance the expression of claudin-1 by binding to its promoter region." (PMID 28350854, 2017). "It has been reported that claudin-18 expression has been shown to have prognostic value in gastric cancer and claudin-3,-4 and-7 expression are similarly elevated in gastric cancer." (PMID 23919729, 2013). "The genes CLDN3, ADH4, and TFF3 have all been implicated in the development of gastric cancer." (PMID 37153834, 2023). "Finally, we identified a gene set associated with the differentiation status of gastric cancer, including AGR3, CLDN3, CLDN4, FABP1, LGALS4, PHGR1, MYH14 and S100A14." (PMID 36729271, 2023). "The influence of claudin-3, claudin-7, and claudin-18 in gastric cancer patients were also studied." (PMID 31861759, 2019). "In a study of gastric cancer, claudin-3 has also been shown to be less expressed in advanced stage cases, which may suggest that claudin family expression patterns vary by cancer type." (PMID 21255442, 2011). "Claudin-3 (CLDN3) has been found to be upregulated in ovarian, breast, laryngeal, and intestinal-type gastric cancers." (PMID 38540693, 2024). "Although ADCC was dependent on CLDN3 expression, ADCC was lower in the human pancreatic cell line AsPC-1 than in the gastric cancer cell line SNU-216 which has lower CLDN3 expression." (PMID 31905631, 2019). "In this regard, PTEN activity has recently been shown to induce an intestinal differentiation of gastric carcinomas by increasing CDX2, claudin-3 and claudin-4 expression, hence supporting this hypothesis." (PMID 21203412, 2010).
colon carcinoma (15 papers, 2017 to 2025). "Genetic and pharmacological studies confirmed that claudin-3 loss induces Wnt/β-catenin activation, which is further exacerbated by Stat-3-activation and helps promote colon cancer." (PMID 34638619, 2021). "The loss of CLDN3 induces Wnt/β-catenin activation in colon cancer, while downregulation of CLDN4 results in E-cadherin loss and increased β-catenin signalling." (PMID 32093760, 2020). "For instance, genetic and pharmacological studies confirmed that the expression of CLDN3 was downregulated in colon cancer and that the loss of CLDN3 induced Wnt/β-catenin activation in a transducer and activator of transcription 3 (Stat3)-dependent manner to promote colon cancer malignancy." (PMID 30219077, 2018). "CPE targets the transmembrane tight junction proteins claudin-3 and claudin-4 receptors, which are overexpressed in several cancers including colon carcinoma." (PMID 39858007, 2025). "The study demonstrated that optCPE gene transfer is a promising strategy for targeted claudin-3- and -4-overexpressing colon carcinomas, resulting in cellular membrane permeability and generating a calcium influx, triggering rapid apoptosis." (PMID 39858007, 2025). "Epidermal growth factor (EGF) promotes the accumulation of claudin-3 in the human colon cancer HT-29 cell line." (PMID 40723233, 2025). "Elevated Cldn expression level, particularly Cldn3/4, has been reported in various types of solid cancer (e.g., PC, ovarian, breast, prostate and colon cancer)." (PMID 34503203, 2021). "By this, Capan-1, PA-TU-8902, AsPc-1 and the positive control human colon cancer HT-29 control cells showed high Cldn3/4 mRNA levels, whereas moderate levels of Cldn3/4 were detected in MIA PaCa-2 and HUP-T3 cells." (PMID 34503203, 2021). "In our previous study, we demonstrated selective and efficient antitumoral efficacy of CPE gene therapy in Cldn3/4 overexpressing colon cancer PDX." (PMID 34503203, 2021). "In contrast, other claudins negatively regulate WNTsignaling cascades, such as loss of claudin-3 inducing WNT/β-catenin activation, thus aiding in the promotion of colon cancer." (PMID 31861759, 2019). "Treatment with Rottlerin resulted in decreased expressions of EpCAM, E-cadherin, and claudin-3 both at mRNA and protein levels in all colon cancer cells." (PMID 30289336, 2019). "The applicability of CPE, claudin-3, and -4 interactions is exploited in gene therapy against colon cancer." (PMID 31861759, 2019). "Further, the depletion of claudin-3 induced tumor burden by enhancing β-catenin activity through (IL)-6/STAT3 signaling in colon cancer." (PMID 31861759, 2019). "Based on this, the present approach is employing CPE gene therapy to selectively eradicate claudin-3 and -4 expressing colon carcinomas as a new strategy for this tumor entity." (PMID 28193196, 2017). "Claudin-3 and -4 overexpressing colon carcinoma lines showed high sensitivity towards both recCPE application and optCPE gene transfer." (PMID 28193196, 2017). "Our approach aimed at evaluation of a selective and targeted cancer gene therapy of claudin-3- and/or claudin-4- expressing colon carcinoma in vitro and in vivo by using translation optimized CPE expressing vector." (PMID 28193196, 2017). "CLDN3 regulates tight junctions of cell-cell adhesion in epithelial or endothelial cells and is overexpressed in ovarian and colon cancer." (PMID 29285217, 2017). "All experiments were performed in the human SW480, SW620, HCT116, CaCo-2 and HT-29 colon cancer and the isogenic Sk-Mel5 and Sk-Mel5 Cldn-3-YFP melanoma cell lines." (PMID 28193196, 2017). "In this study we demonstrated, that colon cancer cells also overexpress claudin-3 and-4, which therefore represents the potential target for CPE therapy." (PMID 28193196, 2017). "More importantly, siRNA-mediated down-regulation of claudin-3 and -4 in colon cancer cells led to decreased responsiveness of these cells towards CPE toxicity." (PMID 28193196, 2017).
colon carcinoma (continued). "In fact, we did use in our in vivo optCPE gene transfer experiment the Co7515 PDX model, which highly expresses claudin-3 and -4 and is derived from lung metastasis of colon cancer." (PMID 28193196, 2017). "In this study the recombinant CPE and a translation optimized CPE expressing vector (optCPE) was used for targeted gene therapy of claudin-3 and/or -4 overexpressing colon cancer cell lines." (PMID 28193196, 2017). "Here, we use in vitro and in vivo approaches to demonstrate that claudin-3 and -4 expressing human colon cancers can be successfully treated by CPE gene transfer." (PMID 28193196, 2017). "Nevertheless, in one study about loss of claudin-3 expression in colon cancer, authors found that claudin-3 depletion did not affect colonic expression or cellular localization of cluadin-1, -2 or -7 proteins, known to be altered in colon cancer." (PMID 36261482, 2022). "The results showed that the CPE is a gene transfer system and can be considered as an appealing therapeutic agent in colon carcinomas through the targeting of claudin-3 and/or claudin-4 which lead to rapid and impressive tumor cell killing in both in vitro and in vivo conditions." (PMID 34281519, 2021). "In our study, the level of claudin-3 was significantly increased in rat colon tumors." (PMID 34638619, 2021). "This novel approach demonstrates that optCPE gene transfer represents a promising and efficient therapeutic option for a targeted suicide gene therapy of claudin-3 and/or claudin-4 overexpressing colon carcinomas, leading to rapid and effective tumor cell killing in vitro and in vivo." (PMID 28193196, 2017). "Numerous studies have shown that colon carcinoma and other epithelial tumors exhibit increased claudin-3 and/or -4 expression, suggesting that CPE might selectively target such tumors." (PMID 28193196, 2017). "By screening of 27 colon carcinoma PDX for claudin-3 and/or -4, the clinical relevance of this approach was further supported, as 20 out of 27 PDX models showed both, claudin-3 and claudin-4 expression, whereas 3 revealed the expression of only claudin-3, suggesting, that binding of CPE can occur." (PMID 28193196, 2017). "This approach demonstrates that CPE gene transfer could be a promising and efficient option for a targeted suicide gene therapy of claudin-3 and/or -4 expressing colon carcinoma." (PMID 28193196, 2017). "Likewise, claudin-3 knockout in mice induced the Wnt/β-catenin signaling pathway, which was further exacerbated by impaired intestinal barrier function and inflammation, hence promoting colon cancer development." (PMID 40723233, 2025). "CMS4 was characterized by suppression of claudin 2, claudin 3, claudin 7, and occludin and upregulation of claudin 5 mRNAs, not aligning with any of the three TCGA genomic groups or with CMS2 despite the similarities in the prevalence of common colon cancer mutations." (PMID 37998722, 2023). "In the colonic tumors of rats with DMH-induced carcinogenesis, the expression of claudin-3 and -4 was significantly increased compared to controls." (PMID 34638619, 2021). "In addition to the previous described knock-in experiments, we also performed knock-down experiments in the human colon cancer cell lines HCT116 and SW480 by using short interfering RNA, targeting claudin-3 and -4 to proof the important role of the claudins in the CPE mediated effect." (PMID 28193196, 2017). "The down-regulation of both claudins (siCldn3 + siCldn4) led to a significantly reduced responsiveness of the colon cancer cells towards recCPE treatment and optCPE gene transfer compared to control (siCo) treated cells, demonstrating specific activity of CPE to its receptors claudin-3 and -4." (PMID 28193196, 2017).